EDA2R (ectodysplasin A2 receptor)
Diseases named in the same sentence as EDA2R in open-access papers (continued):
Sharing a sentence is not in itself a finding about the gene and the disease.
tumor (15 papers, 2017 to 2025). "The researchers found significant upregulation of Eda2r mRNA in the skeletal muscles of tumour‐bearing mice compared to controls." (PMID 41185962, 2025). "EDA2R signalling has recently been described as playing a prominent role in tumour‐induced muscle wasting." (PMID 39001644, 2024). "Our recent work demonstrated that the EDA2R signalling mediates tumour‐induced Atrogin1 and MuRF1 expression in muscle tissue, placing EDA2R at upstream of these atrophy markers." (PMID 39001644, 2024). "It is likely that EDA2R upregulation in the cachectic myonuclei contributes to the transcriptional reprogramming taking place after tumour inoculation." (PMID 39001644, 2024). "The proteins PLK1, SPIB, and CD24 show darker staining in tumor tissues, while NTRK3 and EDA2R exhibit lighter staining in tumor tissues." (PMID 39596658, 2024). "The overlap between the gene set enrichment of EDA‐A2‐treated myotubes and type IIb myonuclei argues that EDA2R upregulation in the cachectic myonuclei likely contributes to the transcriptional reprogramming taking place after tumour inoculation." (PMID 39001644, 2024). "Through our analysis of the tumor microenvironment, we made an intriguing discovery regarding the relationship between EDA2R expression and the proportion of immune-infiltrating cells." (PMID 37904416, 2023). "This signature consists of 5 genes (HOTAIR, PLK1, LAMA3, EDA2R, and IKZF3) that are closely linked to tumor development." (PMID 37904416, 2023). "The relationship between EDA2R transcription and prognosis in various tumor types was examined using the KM Plotter database." (PMID 37904416, 2023). "In fact, GSEA demonstrated that EDA2R activation and tumour inoculation led to similar expression patterns in muscle cells, including the stimulation of NFκB, JAK–STAT and TGFβ pathways and the suppression of myogenesis, oxidative phosphorylation and fatty acid oxidation." (PMID 39001644, 2024). "Muscle oxidative metabolism was suppressed by both tumours and EDA2R activation." (PMID 39001644, 2024). "These upregulated genes (Cdkn1a, Eda2r and Phlda3), are known for their role in cell cycle arrest, apoptosis and tumor suppression, while the most downregulated genes (Hba-a2, Serpina9, and Ms4a1) are associated with hemoglobin synthesis, mitochondrial function and B cell differentiation 34–43." (PMID 36604457, 2023). "Could EDA2R activation drive the production of specific metabolites that, in turn, facilitate tumor growth?" (PMID 37807033, 2023). "Based on our findings, EDA2R may have an impact on tumor prognosis through its influence on the tumor microenvironment." (PMID 37904416, 2023). "Notably, Eda2r‐deficient mice were resistant to tumour‐induced muscle wasting and did not exhibit the typical enrichment of type IIb myofibers or the reduction in fibre cross‐sectional area seen in wild‐type mice." (PMID 41185962, 2025). "Similarly, the cross‐sectional area of the EDA2R‐deficient myofibers did not change significantly upon tumour growth." (PMID 39001644, 2024). "Dr. Serkan Kir (Koç University, Turkey) showed that EDA2R (Ectodysplasin A2 Receptor) and OSM (Oncostatin M) were highly upregulated in muscle from tumor-bearing mice." (PMID 41245273, 2025). "EDA2R (XEDAR) is a tumor suppressor that prevents apoptosis and anoikis by regulating tumor progression." (PMID 39596658, 2024). "The mRNA expression of SPIB, PLK1, and CD24 is upregulated in clinical tumor tissues, whereas NTRK3 and EDA2R mRNA expression is downregulated." (PMID 39596658, 2024). "In clinical tumor tissues, protein expression of SPIB, PLK1, and CD24 was up-regulated, while protein expression of NTRK3 and EDA2R was down-regulated." (PMID 39596658, 2024).
tumor (continued). "RELT and TNFSF10 had high expression levels in tumor tissues compared with normal tissues, while EDA2R and TNFSF18 had low expression levels in tumor tissues compared with normal tissues in TCGA dataset." (PMID 34484286, 2021). "The researchers demonstrate that EDA2R-NIK signaling is integral to tumor-induced muscle wasting through activation of the non-canonical NF-κB pathway." (PMID 37807033, 2023).
cardiovascular disease (1 paper, 2025). "Together, these studies provide both epidemiological and mechanistic evidence supporting EDA2R as a promising biomarker and potential therapeutic target in cardiovascular disease." (PMID 41185962, 2025).
EDA2R also shares sentences with these, for which no sentence is quoted: ectodermal dysplasia (2 papers); alopecia (1); breast tumors (1); cervical squamous cell carcinoma (1); Cognitive impairment (1); colorectal carcinoma (1); coronary atherosclerosis (1); demyelination (1); Duchenne muscular dystrophy (1); facioscapulohumeral muscular dystrophy (1); hair diseases (1); head and neck squamous cell carcinoma (1); Insulin resistance (1); ischemic heart disease (1); kidney failure (1); lung carcinoma (1); metabolic disease (1); muscle degeneration (1); neurologic disease (1); neuropathies (1); osteosarcoma (1); Pituitary adenoma (1); rectal adenocarcinomas (1); rheumatic disease (1); sarcoma (1); Sjögren’s syndrome (1); stomach adenocarcinoma (1); systemic sclerosis (1); thymoma (1); type 2 diabetes (1).
A further 2 diseases each share a sentence with EDA2R in 1 paper.